KRAS (KRas proto-oncogene, GTPase)
Diseases named in the same sentence as KRAS in open-access papers (continued):
Sharing a sentence is not in itself a finding about the gene and the disease.
tumor (continued). "However, recent studies with KRAS mutant-specific inhibitors note similar TME changes suggesting that the majority of effects observed with our pan KRAS inhibitors are likely driven by on-target tumor cell-intrinsic effects." (PMID 38727236, 2024). "We included in our study also n = 4 patients whose tumor harbored concurrent currently non-actionable KRAS and BRAF mutations, considering their potential future targetability with novel KRAS and BRAF inhibitors." (PMID 39124743, 2024). "In Mia PaCa‐2 cells, the suppression of GSK‐3β inhibits mutant KRas‐dependent tumor growth and the depletion of GSK‐3β increases β‐catenin levels and forces the expression of β‐catenin mutants that lack GSK3 phosphorylation sites and are thus insufficient to induce apoptosis." (PMID 39632551, 2024). "A plasma sample at this time revealed both mutations, but also a KRAS G12A mutation that had been absent in the initial tumor." (PMID 38806586, 2024). "Three patients had at least one activating KRAS alteration and/or KRAS amplification detected in all samples, with the ERBB2 amplification occurring in the last sample, notably corresponding to an increase in tumor shed, as measured via the maximum variant allele frequency (maxVAF) in the sample." (PMID 38406801, 2024). "The tumor location analysis did not reveal a significant association between KRAS mutations and the colon's right or left side (p-value = 0.655)." (PMID 38465160, 2024). "Based on these results, we speculate that SPTBN2 overexpression and KRAS activation may interact to promote tumor growth and inhibit the penetration of CD8 + T cells in PAAD." (PMID 38684762, 2024). "RNA-based therapies, such as siRNA or ASOs that target KRAS, can effectively reduce its expression, which may lead to decreased tumor growth and improved treatment responses." (PMID 39857631, 2024). "It remains to be explored whether SGs function as protective reservoirs for proteins, enabling rapid adaptation to the fluctuating demands of the hostile tumor microenvironment of KRAS-driven PDAC." (PMID 38413839, 2024). "Mutation of the KRAS gene, a member of the RAS family, can lead to continued activation of the RAS protein, thereby causing abnormal cell growth and proliferation and promoting tumor development." (PMID 39927117, 2024). "Additionally, the deletion of SLC7A11 selectively induced ferroptosis in pancreatic ductal adenocarcinoma cells driven by the KRAS proto-oncogene, effectively impeding tumor growth." (PMID 38475936, 2024). "Importantly, KRAS also amplified macropinocytosis by tumor cells, promoted the rate of extracellular protein transport into the cells, and increased glutamine production after proteolytic degradation of various internalized proteins." (PMID 38172980, 2024). "Moreover, we found that Id1 plays a major role in the acquired resistance to trametinib treatment in KRAS-mutant LUAD tumor cells." (PMID 38643157, 2024). "Proximal C9 cells clustered separately from other tumor cells and showed senescent phenotype, while distal C4 spots exhibited hypermetabolic features and higher activity of oncogenic pathways, such as KRAS and EGFR signaling as well as DAP12 interactions (with myeloid cells)." (PMID 38645221, 2024).
tumor (continued). "The tumor microenvironment plays a significant role in resistance to KRAS inhibitors." (PMID 38668053, 2024). "Therefore, it is highly likely that a combination approach with KRAS and immuno-oncology (I/O) to target both tumor proliferation and antitumor immunity will be needed to circumvent KRAS-targeted resistance." (PMID 38727236, 2024). "In order to increase oncogenicity and proliferate, KRASG12C hyperactivates KRAS signaling which may be relevant to KRASG12C-driven tumor evolution." (PMID 39533328, 2024). "However, the average percent tumor content from slides taken throughout the core had a strong positive correlation with KRAS VAF." (PMID 38291365, 2024). "MRTX1133, a potent, selective, and non-covalent KRASG12D inhibitor, exhibited a dose-dependent inhibition of KRAS-mediated signal transduction and marked tumor regression (≥30%) in a subset of KRASG12D-mutant cell line-derived and patient-derived xenograft models, including 8/11 (73%) PDAC models." (PMID 39062863, 2024). "In tumour-agnostic studies, ctDNA samples are analysed without prior examination of tumour tissue, and therefore target frequently mutated genes such as KRAS, or epigenetic changes such as hypermethylation in the promotor regions of tumour suppressor genes." (PMID 39409954, 2024). "It is well known that KRAS gene inhibits the growth of tumor cells." (PMID 38694509, 2024). "However, like other drugs, resistance to KRAS inhibitors is expected, and the drug penetrance to the tumor TME is also a confounding factor for their efficacy." (PMID 39518005, 2024). "PFS and OS did not significantly differ according to the primary tumor location, the location of metastases, or the presence or absence of KRAS mutations." (PMID 38893113, 2024). "Additionally, granulocyte macrophage colony stimulating factor (GM-CSF) secretion in response to mutated KRAS, can occur early and promotes MDSC infiltration, restricting anti-tumor immunity." (PMID 38576709, 2024). "The two enantiomers of VC known as the L- and D-forms of ascorbic acid (D-VC and L-VC) in combination with arsenic trioxide have a similar potent cytotoxic oxidizing effect on cancer cells, but the use of D-VC has been shown to be more effective in suppressing KRAS mutant tumor growth." (PMID 38473779, 2024). "Meanwhile, KRAS mutations were not correlated with age, smoking status, drinking history, serum tumor markers, histological types, nodule types, or TNM stage." (PMID 39364008, 2024). "These genes, including ERBB2, CCNA1, FOXC2, LEFTY2, VTN, ACKR3, and PTGS2, are involved in key processes like apoptosis, epithelial–mesenchymal transition, angiogenesis, response to hypoxia, and KRAS signaling pathways, which are crucial for tumor virulence and the spread of metastases." (PMID 39000413, 2024). "A study showed the knockdown of KRAS mutation (G12D) in a poorly immunogenic CRC model could improve the immune response and resulting in tumor regression." (PMID 38097680, 2023).
tumor (continued). "At EOT, c.35G>C KRAS was still detected in CTCFAPα, but a new c.35G>T (p.G12V) KRAS was now detected in both CTCFAPα and CTCEpCAM subpopulations, possibly indicating the evolution of a different clone of tumor cells ~120 days after treatment." (PMID 37759489, 2023). "Although the role of KRAS mutation in tumorigenesis and tumor maintenance has been extensively studied, the relationship between KRAS and the tumor immune microenvironment is not fully understood." (PMID 36413402, 2023). "Previously, KRAS testing was performed on tumour tissue, where DNA is extracted from formalin-fixed paraffin-embedded (FFPE) tissue blocks, followed by a variety of polymerase chain reaction (PCR)-based testing methods including sanger sequencing and pyrosequencing." (PMID 38067288, 2023). "Despite the low sample size, these findings could imply that KRAS wild-type CTCs are often found in the peripheral blood of patients harbouring mutant primary tumours." (PMID 37761948, 2023). "A margin smaller than 5 mm is no longer to be considered acceptable for local tumor control, especially in patients with KRAS-confirmed mutation." (PMID 38136351, 2023). "We sought to define if KRAS mutant clones were already present in the primary tumor or any of the successive available tumor samples but could not identify the preexistence of KRAS mutation." (PMID 36967525, 2023). "Nevertheless, these findings support a vital role of M2 macrophage polarization and a role of IL10 and IL6/STAT3 signaling in HES1 (−) KRAS mutant CRCs that may act in concert to promote tumor progression and metastasis." (PMID 37749297, 2023). "The observed correlation between cytotoxic CD8+ T‐cell tumor infiltrate and KRAS mutation in clinical samples does not necessarily indicate mutant KRAS was a causative factor in reducing tumor‐infiltrating cytotoxic CD8+ T‐cells." (PMID 36599679, 2023). "We foresee the necessity of further studies that examine the targeting both of tumor-intrinsic factors and proinflammatory and immunosuppressive TMEs to better cover the complexity of KRAS-mutant NSCLC and provide more personalized treatment based on the genetic assessment of each patient." (PMID 36899885, 2023). "Results indicated cytotoxic CD8+ T‐cell tumor infiltrate was unlikely to correlate with KRAS mutation type by demonstrating comparable tumor‐infiltrating cytotoxic CD8+ T‐cell density in CRC tissues with different types of KRAS mutations." (PMID 36599679, 2023). "Therefore, even though these drugs are not designed to treat cancer, they can inhibit the growth of tumor cells in different ways and can also be used to treat KRAS mutants CRC." (PMID 38023258, 2023). "We found a single tumor with a duplication of the KRAS gene." (PMID 36635367, 2023). "Some of these new findings might prove important to explain the differences among KRAS mutant proteins in the promotion of cell transformation, tumour development, drug sensitivity, and maintenance of human tumours." (PMID 37627169, 2023). "In addition, let-7g exerts tumor-suppressive effect by imperfectly base-pairing with the 3′-untranslated region (UTR) of kirsten rat sarcoma viral oncogene homolog (KRAS) mRNA to regulate the oncogenesis of cancer cells." (PMID 37759534, 2023). "In addition, intolerance for repeated invasive procedures in tumor patients required alternatively noninvasive methods to determine KRAS status." (PMID 38087207, 2023). "Moreover, hotspot KRAS mutations were identified in these lesions, placing them in the spectrum of RAS–MAPK-driven neoplasms, which were until recently thought to be reactive lesions." (PMID 37627135, 2023). "Here, we identified a role of KRAS in driving tumor evasion from innate immune surveillance." (PMID 36413402, 2023).
tumor (continued). "Thus, when considering all tumors independently of their engineered tumor suppressor inactivation, KRAS G12C drives substantially less neoplastic growth than KRAS G12D." (PMID 37828026, 2023). "KRAS signaling also dampens the function of tumor-infiltrating T cells via numerous mechanisms." (PMID 37581538, 2023). "In addition, different pockets and domains that can accommodate compounds have been defined in the allosteric lobe and, interestingly, some of these compounds can inhibit KRAS signaling and reduce cancer cells’ viability or tumor progression in mouse models." (PMID 36614192, 2023). "Furthermore, TRAIL death receptor 2 is overexpressed in KRAS-mutated tumors, and this overexpression activates the Rac1/PI3K pathway, which in turn promotes KRAS-driven tumor progression, invasion, and metastasis." (PMID 37345089, 2023). "Across tumor types, KRAS-mutated tumors had a higher TMB versus KRAS wild-type tumors (P = 3 × 10−22, Wilcoxon rank-sum; P = 0.013 after controlling for MSI status using MANTIS) but was also lost after controlling for tumor type (P = 0.58, multivariate linear regression)." (PMID 37558751, 2023). "Mutational status in tumor tissue comprised 14 patients (67%) with KRAS mutations, nine without detection of KRAS, NRAS, or BRAF mutations (wild-type), and four without available mutational testing." (PMID 37903871, 2023). "The comparison between codon 12 KRAS and codon 13 KRAS mutations according to tumor localization did not reveal significant differences (p = 0.430)." (PMID 37628934, 2023). "In particular, we will discuss how our understanding of tumour cell-intrinsic KRAS signalling and PD-L1 expression has evolved in relation to anti-tumour immunity and mechanisms of immune escape, and how this is driving innovation in research and clinical settings." (PMID 36864508, 2023). "Meanwhile, we demonstrated that in vivo ARL-17477 inhibits the tumor growth of KRAS-mutant cancer." (PMID 37402770, 2023). "After tumor mutation profile and copy number variation (CNV) analyses, we established and validated a prediction model of KRAS mutations, based on survival analysis and mRNA expression, that contained seven genes: CSTF2, FAF2, KIF20B, AKR1A1, APOM, KRT6C, and CD70." (PMID 38268915, 2023). "Our results demonstrated that internalized anti-KRAS antibody inhibits KRAS function in tumor." (PMID 37051535, 2023). "Moreover, deltaflexin selectively inhibits oncogenic KRAS-driven cell proliferation and tumor formation." (PMID 37669923, 2023). "The consistent results across tumours suggest that a PITPNC1-regulated network represents a relevantly common signalling node in KRAS oncogenesis with clinical implications that could be exploited for therapeutic purposes." (PMID 37210549, 2023). "Finally, we demonstrate that siRNA nanoparticles targeting SLC25A22 synergizes with anti-PD1 to suppress tumor growth in KRAS-mutant CRC." (PMID 37542037, 2023). "The results showed that genetic mutations in EGFR, KRAS, and BRAF could be successfully detected in the collected tumor cells even when there was only one tumor cell (sample numbers 4 and 15)." (PMID 37849806, 2023). "According to preclinical studies, adagrasib effectively and consistently blocks KRAS-dependent signaling pathways with long-lasting effects, resulting in substantial tumor regression in 17 out of 26 (65%) KRAS-G12C-positive cell line- and patient-derived xenograft models." (PMID 37662925, 2023). "Regardless of age of onset, a tumor harboring a KRAS variant sequence was found to be more prevalent arising from the right compared with the left colon." (PMID 38032636, 2023).
tumor (continued). "We first used this workflow on tumor cell lines, including H1650, PANC-1, and HT-29, to assess whether the most common genetic mutations in EGFR (19del), KRAS (G12D), and BRAF (V600E)." (PMID 37849806, 2023). "It has been hypothesized that KRAS, NRAS, or BRAF mutations and deficient mismatch repair status (MMR) might be partially responsible for the prognostic effect of primary tumor location." (PMID 37071802, 2023). "The specificity in this study reflects the correlation between the primary tumor tissue and the liquid biopsy and not the overall specificity of KRAS mutational status for PDAC diagnosis." (PMID 37189687, 2023). "It was found in the cytoplasm and at the cell membrane and correlated with diverse clinicopathological patient characteristics, including tumor type according to the Lauren, mucin phenotype, microsatellite status, E-cadherin and β-catenin expression, KRAS genotype and PD-L1 status in tumor cells." (PMID 36976399, 2023). "Furthermore, the correlation between BRAF, KRAS, NRAS mutations, and FAP and CXCR4 in both the primary tumor and the first metastasis were examined." (PMID 37892020, 2023). "Also, among the hub genes of the NAT, SN, and SNAT lists, COL1A2 (12%), KRAS (14%), and VCAN (9%) have a higher mutation rate in tumour samples, respectively." (PMID 37118990, 2023). "To verify the fibroblastic nature of the isolated cells, we showed by Western blot that only KPfC-derived tumor cells but not CAFs expressd a high level of mutated KRas G12D." (PMID 37643024, 2023). "These differential affinities of KRAS mutants for SOS1 might have important implications in tumours, as KRAS binds to SOS1 in the enzymatic pocket but can also regulate its function by binding to an allosteric regulatory pocket." (PMID 37627169, 2023). "The most common KRAS mutation, G12D, is found in 29.5% of all cancers, and 40–50% of PDAC tumours." (PMID 36864508, 2023). "A study found that exosomes loaded with clustered regularly interspaced palindromic repeats (CRISPR)/Cas9 could target the KRAS G12D-mutant allele in PDAC cells to suppress cell proliferation and tumor growth, making it a promising treatment strategy." (PMID 36675641, 2023). "Furthermore, the impact of different tumor suppressors on tumor number varied across oncogenic KRAS, BRAF, and EGFR contexts." (PMID 37828026, 2023). "In our cohort, the molecular evaluation of RAS mutational status in tumor tissue samples, performed by NGS, confirmed a low frequency of both KRAS and NRAS mutations in mCRC patients, which is in agreement with the data reported in the literature for this type of tumor (1–5% for mCRC)." (PMID 37296579, 2023). "Intratumor heterogeneity is one of the reasons for this discordance, suggesting that both KRAS wild-type and mutant subpopulations of cells may coexist within the same tumour and compete with one another for shedding into the bloodstream." (PMID 37761948, 2023). "Despite comparable expression of AICD mediators in T‐cells (FasL, TNF, and TRAIL) from KRAS mutant versus wild‐type tumors, markedly increased apoptosis was observed in the tumor‐specific CTLs from KRAS mutant tumor tissues after cells were cocultured with autologous primary tumor cells." (PMID 36599679, 2023).